DPPA4 (developmental pluripotency associated 4)
Description:
May be involved in the maintenance of active epigenetic status of target genes. May inhibit differentiation of embryonic cells into a primitive ectoderm lineage.
Synonyms: FLJ10713; 2410091M23Rik
Tractability: PROTAC: ubiquitination databases record sites on it.
Gene: Protein-coding gene on chromosome 3 (109,326,144 to 109,337,591, reverse strand). Ensembl gene ENSG00000121570.
Subcellular location: Nucleus
Subcellular location (Human Protein Atlas): Nucleoli; Nucleoli rim; Cytosol; Mitotic chromosome; Nucleoplasm
Pathways (Reactome):
Developmental Biology: POU5F1 (OCT4), SOX2, NANOG activate genes related to proliferation; Zygotic genome activation (ZGA)
Gene Ontology:
Molecular function: protein binding; chromatin binding
Biological process: system development
Cellular component: nucleoplasm; nucleus
Genetic constraint (gnomAD): Loss-of-function variants: 21 observed, 33.55 expected, observed/expected ratio (o/e) 0.63, 90% interval 0.44 to 0.9. The upper end of that interval is the gene's LOEUF score, 0.9, which puts it in group 3 of 6, group 1 being the genes least tolerant of losing a copy. Missense variants: 324 observed, 358.72 expected, observed/expected ratio (o/e) 0.9, 90% interval 0.82 to 0.99. Synonymous variants: 148 observed, 134.27 expected, observed/expected ratio (o/e) 1.1, 90% interval 0.96 to 1.26.
Homologues: Orthologues: macaque DPPA4 (94% identical), chimpanzee DPPA4 (76% identical), pig DPPA4 (56% identical), rat Dppa4 (52% identical), mouse Dppa4 (50% identical), tropical clawed frog dppa2 (17% identical). Paralogues in human: DPPA2 (40% identical).
Diseases named in the same sentence as DPPA4 in open-access papers:
DPPA4 is named in the same sentence as 11 diseases in open-access papers, as found by Europe PMC text mining. Sharing a sentence is not in itself a finding about the gene and the disease. The quoted sentences say what the papers report.
embryonal carcinoma (2 papers, 2019 to 2025). A non-seminomatous malignant germ cell tumor characterized by the presence of large germ cells with abundant cytoplasm resembling epithelial cells, geographic necrosis, high mitotic activity, and pseudoglandular and pseudopapillary structures formation. "Genes such as DPPA4 and PSMA7 were highly expressed in tumor cells characterized by elevated stemness and enhanced metastatic ability, including embryonal carcinoma and metastatic seminoma, and were linked to disease progression in TCGA analyses." (PMID 41203637, 2025). "Furthermore, Dppa4 similarly bound to Dux in P19 embryonal carcinoma cells but not in 3T3 fibroblasts." (PMID 30692203, 2019).
bladder carcinomas (1 paper, 2015). "Dppa4 re-expression has been found in tissue samples of colon, prostate, and bladder carcinomas as well as cancer cell lines HT-29, Caco-2, HT-1376, LNCaP, and HepG2." (PMID 26063247, 2015).
colon cancer (1 paper, 2015). "Therefore, Dppa4 is associated with malignant transformation of colon cancer and is a potential target for cancer prevention and treatment." (PMID 26063247, 2015). "Individuals with Dppa4-positively stained tumors experienced shorter OS and DFS, indicating Dppa4 as a novel prognostic biomarker of colon cancer outcome." (PMID 26063247, 2015). "Real-time polymerase chain reaction and Western blotting were used to evaluate Dppa4 mRNA and protein expression in 39 pairs of fresh-frozzen colon cancer samples, which were compared with adjacent normal mucosa." (PMID 26063247, 2015). "Both the mRNA and protein level expression of Dppa4 gene was found to be upregulated in colon cancer tissues." (PMID 26063247, 2015). "In summary, the present study identified that the Dppa4 mRNA and protein expression was upregulated in the colon cancer samples." (PMID 26063247, 2015). "In univariate analysis, patients with Dppa4-positively stained colon tumors had an obviously lower DFS and OS than those with Dppa4-negative tumors [DFS, HR 6.118 (95 % CI 3.004–12.462); OS, HR 6.348 (95 % CI 2.875–14.014)]." (PMID 26063247, 2015). "RNA interference (RNAi) technology was carried out to access the role of Dppa4 in colon cancer cells." (PMID 26063247, 2015). "The clinicopathologic significance of Dppa4 expression was further determined by immunohistochemical analysis on a tissue array containing 185 cases of primary colon cancer paired with normal tissue and 63 cases of available metastatic lymph nodes." (PMID 26063247, 2015). "By knockdown of Dppa4 expression with shRNA, we also investigated the effects of Dppa4 on colon cancer proliferation and its possible mechanisms." (PMID 26063247, 2015). "In a study of expression of stem cell-specific marker genes in multiple malignant tumors, Dppa4 was found to be significantly expressed in cancer cell lines and cancer tissues, including colon cancer and colorectal cell lines." (PMID 26063247, 2015). "The average Dppa4 expression (ΔCt value) in the colon tumor group was 5.17 ± 0.37 whereas in the normal tissue group, it was 8.90 ± 0.55 (P < 0.01), indicating that the Dppa4 mRNA level was upregulated in cancer tissues than in paired normal mucosa." (PMID 26063247, 2015). "The current study was aimed to access the expression of Dppa4 at both transcriptional and translational levels and its predictive value in colon cancer." (PMID 26063247, 2015). "Kaplan-Meier analysis also revealed that Dppa4 expression was significantly relevant to OS of colon cancer patients (log-rank test, P < 0.001)." (PMID 26063247, 2015). "We investigated whether Dppa4 is an independent biomarker that could predict metastasis and prognosis in patients with colon cancer." (PMID 26063247, 2015). "However, the clinicopathological significance of Dppa4, and its possible mechanism in colon cancer tumorigenesis and progression is still unclear." (PMID 26063247, 2015). "Dppa4 was also a significant independent prognostic factor for colon cancer." (PMID 26063247, 2015). "Dppa4 was also shown to be an independent prognostic indicator of disease-free survival (HR 6.118, 95 % CI 3.004–12.462) and overall survival (HR 6.348, 95 % CI 2.875–14.014) for patients with colon cancer." (PMID 26063247, 2015). "Dppa4 overexpression was associated with poor OS and DFS of colon cancer patients." (PMID 26063247, 2015). "The present study investigates the expression and clinical significance of Dppa4 in colon cancer." (PMID 26063247, 2015). "In this study, we explored the expression pattern of DPPA4 in colon cancer samples and cell lines." (PMID 26063247, 2015).
colon cancer (continued). "The results indicate that Dppa4 might play an important role in colon cancer progression and function as a novel prognostic indicator and a potential therapeutic target." (PMID 26063247, 2015). "However, the prognostic potential role of Dppa4 in human colon cancer and its potential role in the pathogenesis and progression of colon cancer still remain unclear." (PMID 26063247, 2015). "Among the 39 paired cases, 25 (64.1 %) colon cancer tissues showed at least a 2-fold increase in Dppa4 mRNA level compared with its adjacent non-cancerous mucosa." (PMID 26063247, 2015). "Finally, by univariate and multivariate Cox model analyses, we confirmed Dppa4 to be an independent prognostic factor for DFS and OS in colon cancer." (PMID 26063247, 2015).
colorectal cancer (1 paper, 2015). A primary or metastatic malignant neoplasm that affects the colon or rectum. "Knockdown of Dppa4 expression inhibited the proliferation of colorectal cancer cell lines through G1/S transition regulation." (PMID 26063247, 2015). "The effect of Dppa4 knockdown on colorectal cancer cell proliferation was investigated using Cell Counting Kit-8 (CCK8) assays and colony-formation assays." (PMID 26063247, 2015). "Our results showed for the first time that over-expression of Dppa4 was significantly associated with unfavorable clinicopathological variables and Dppa4 might be used as a novel prognostic marker for colorectal cancer." (PMID 26063247, 2015).
germ cell tumor (1 paper, 2025). A benign or malignant, gonadal or extragonadal neoplasm that originates from germ cells. "Together, these findings suggest that DPPA4 and PSMA7 promote tumor progression, whereas PAGE5 and SAT1 suppress progression in germ cell tumors." (PMID 41203637, 2025).
myotonic dystrophy (1 paper, 2023). An inherited progressive disorder affecting the muscles. "CNBP is dysregulated in iPSC derived from patients with myotonic dystrophy, whereas SOX4 and DPPA4 are transcription factors shown to be dynamically regulated during endoderm induction from iPSCs." (PMID 36631981, 2023).
cancer (9 papers, 2011 to 2025). A tumor composed of atypical neoplastic, often pleomorphic cells that invade other tissues. "Overexpression of Dppa4 was associated with cancer progression and metastasis." (PMID 26063247, 2015). "Colony formation assay showed that Dppa4 knockdown inhibited cancer cell colonogenicity compared with control groups." (PMID 26063247, 2015). "The mRNA level of proliferation-related gene ki-67 and G1/S transition related genes, CCND1 and TAF10 was evaluated to confirm the effect of Dppa4 knockdown on cancer cell proliferation." (PMID 26063247, 2015). "Moreover, the ethanol‐responsive oncogenic factor DPPA4, which is overexpressed in various cancers, was elevated in PAE male rat pituitaries following estrogen treatment." (PMID 41017273, 2025). "Simultaneously, cancer stemness gene DPPA4 that located at 3q13.13 and was selected in the set of events after GD may contribute to the development and progression of ESCC." (PMID 29348864, 2017). "Expression of DPPA4 has been reported in PCa cell lines but its role in somatic cancer is largely unknown." (PMID 26885621, 2016). "The structure and functions of Dppa4 in biology process indicate the possible mechanism of Dppa4 in cancer progression and it might be a potential therapeutic target." (PMID 26063247, 2015). "Dppa4 was prominently localized in the cytoplasm of the cancer cells and was prominently upregulated in 42.9 % (69 of 185) of primary cancer specimens and 58.7 % (37 of 63) of LNM, whereas the adjacent normal tissue was only 16.2 % (30 of 185), especially in cases with LNM." (PMID 26063247, 2015). "Within community 2, we also identified increased expression of regulators of cell proliferation (CENPE, MKI67, TOP2A, UBE2C, guanine), cancer, and pluripotency (DNMT3B, DPPA4, MYC, POU5F1, CRABP2)." (PMID 33771987, 2021). "We also found that c-JUN facilitates expression of pluripotent genes, such as Klf5, Zfp42, Dppa4 and Esrrb, which is consistent with previous observations that c-JUN plays a pivotal role in the maintenance of self-renewal in cancer stem cells." (PMID 27894081, 2017).
tumor (4 papers, 2015 to 2025). "DPPA4 has been shown to increase stem cell regulatory proteins and promote tumor cell stemness in PAE female rat pituitaries." (PMID 41017273, 2025). "A subset of tumor cells expressing DPPA4 and PSMA7 showed high stemness, enhanced self-renewal, and association with metastasis." (PMID 41203637, 2025). "In multivariate analysis with clinicopathologic parameters, the expression of Dppa4 was found to be an independent prognostic marker to predict tumor recurrence." (PMID 26063247, 2015). "The expression of Dppa4 in tumor tissue was examined and compared with paired normal colonic mucosa in 39 patient samples using real-time PCR with GAPDH as the internal reference." (PMID 26063247, 2015). "Knockdown of DPPA4 and PSMA7 significantly reduced the size of tumor spheres in both cell lines." (PMID 41203637, 2025).
infection (1 paper, 2012). The state of being infected such as from the introduction of a foreign agent such as serum, vaccine, antigenic substance or organism. "Genes in regions associated with odds of infection included DPPA2/DPPA4 (empirical P = 0.006), and SYTL3 (P = 0.051)." (PMID 23082221, 2012).
DPPA4 also shares sentences with these, for which no sentence is quoted: seminoma (2 papers); teratoma (1).